TRIM22 (tripartite motif containing 22)
Diseases named in the same sentence as TRIM22 in open-access papers (continued):
Sharing a sentence is not in itself a finding about the gene and the disease.
infection (continued). "Of interest, CTR MDM showed a significant increase in TRIM22 mRNA expression in comparison to their basal levels 8 days after infection." (PMID 30250078, 2018). "Upon infection of the TRIM22-KD and CTRL-KD SupT1 cells with the different HIV-rtTA variants, virus replication was followed up to 32 days post-infection (PI)." (PMID 26683615, 2015). "TRIM22 expression is upregulated in response to infection with rubella virus and Epstein-Barr virus (EBV) and downregulated during infection with human papillomavirus type 31." (PMID 22649727, 2012). "CMPK2 and TRIM22 also modestly reduced infection, indicating that these proteins may have anti-EBOV capabilities and should be further evaluated in future studies." (PMID 41472248, 2025). "TRIM22 was knocked down and overexpressed in HUVECs followed by infection with DENV-2 to further explore whether TRIM22 mediates DENV-2-induced autophagy through the AMPK/ERK/mTOR pathway." (PMID 36587218, 2022). "Importantly, TRIM22 levels in 7134R infection were comparable to levels observed in mock infection, while levels of the known restriction factor IFI16, are reduced in 7134R infection (lane 3)." (PMID 33524065, 2021). "However, unique from its reported role as an effector protein of the IFN-response, we demonstrate that pre-existing levels of constitutive TRIM22 expression are sufficient to restrict the onset of IAV transcription from the outset of infection." (PMID 34621686, 2021). "Indeed, TRIM22 directly interacted with the NP of susceptible IAV strains both in a cotransfection system and during infection, and this interaction was followed by TRIM22-mediated downregulation and ubiquitination of the viral protein." (PMID 34440633, 2021). "To determine whether TRIM22 expression increased during infection, we compared healthy macaques with those infected with IAV (A/California/04/2009 (H1N1); Cal)." (PMID 34621686, 2021). "Furthermore, TRIM22 was previously reported to be upregulated in the first 24h of infection in primary human foreskin fibroblasts (HFFs) with human cytomegalovirus (HCMV), a β-herpesvirus." (PMID 33524065, 2021). "Specific polymorphisms of the TRIM family of RFs, particularly TRIM5α and TRIM22, are associated to important variations in HTLV-1 proviral load, an event that has been correlated with the possible evolution of the infection toward the stronger susceptibility to HAM/TSP." (PMID 31783769, 2019). "We propose that the pre-existing antiviral defence conferred by constitutive expression of TRIM22 may play an important role in protecting the host during the initial exposure of respiratory cells to invading virus, prior to the spread of infection and activation of the innate immune response." (PMID 34621686, 2021). "During our screening of TRIM family proteins in A549 cells following infection with influenza A virus (IAV) or vesicular stomatitis virus (VSV), we observed that TRIM22 was the most prominently upregulated." (PMID 40162781, 2025). "Infection with influenza A virus (IAV) and hepatitis C virus induces upregulation of TRIM22, which in turn limits viral replication." (PMID 37628607, 2023). "A549 cells were transfected with the plasmid overexpressing TRIM22 or an empty vector as control and were subsequently infected with ZIKV (GZ01 strain) at multiplicity of infection (MOI) of 0.1 at 12 h post transfection." (PMID 36042495, 2022). "The results showed that infection of these ZIKV strains also induced mRNA and protein expression of TRIM22, which is consistent with other ISGs, such as MX1, IDO1 and RSAD2." (PMID 36042495, 2022). "TRIM22 depletion increased the expression of ICP27 and ICP8 transcript levels by approximately 3-fold upon infection with the 7134 virus in control fibroblasts at 8 hpi." (PMID 33524065, 2021). "In vitro studies have shown that TRIM22 binds to NS5A, a viral protein that counteracts the IFN-α signaling pathway induced by the infection." (PMID 34440633, 2021).
infection (continued). "The expression of both TRIM22 and CIITA mRNAs was indeed promptly upregulated after 18 h of cell stimulation of MDM with M1 cytokines before infection." (PMID 30250078, 2018). "Notably, multiple antiviral proteins were also dramatically decreased in PAMs during the PRRSV-ADE infection, including ISG15, ISG20, IFIT1 (ISG56), IFIT2 (ISG54), IFIT3 (ISG60), IFIT5 (ISG58), OAS1, Mx1, RSAD2, TRIM22, TRIM25 and TRIM34, except for TRIM52." (PMID 36680075, 2022). "Importantly, the decrease in DAXX protein levels is likely not attributed to a global host protein expression shut down, as the levels of Lamin B, HSP90, Actin, GAPDH, Tubulin, TRIM22 and RIG-I were unchanged upon infection." (PMID 35508460, 2022). "Therefore, we measured the efficiency of EBV-GFP infection in HEK293 cells expressing the EBV receptors, CD21 and HLA-II, after stable transfection with the empty vector (pLPCX) or full-length TRIM22 (TRIM22)." (PMID 33524065, 2021). "TRIM22 is upregulated during the clearance of HCV in chimpanzees, and in response to infection by rubella virus, but also DNA viruses such as Epstein–Barr virus (EBV), although it was downregulated during infection with another DNA virus, human papillomavirus type 31." (PMID 34440633, 2021). "TRIM22 RNA expression and HIV-1 plasma viral loads are negatively correlated in adults in the first year of infection, however, in chronic infection it is unknown if this association persists." (PMID 34870928, 2021). "This was surprising and indicated that infection studies that utilized such cell lines would not capture the potential antiviral properties of endogenous TRIM22 observed in the respiratory tract." (PMID 34621686, 2021). "It is interesting that TRIM22 expression was downregulated upon infection with the pH1N1 virus, but not with the reassortant viruses expressing the WT or R4 sH1N1 NP." (PMID 29624498, 2018). "These cells could produce higher amounts of other antiviral proteins in response to virus such as those observed in this study: MX2, TRIM22, APOBEC3G, and of immunoregulators such as ERAP2, further preventing productive infection." (PMID 28243241, 2017). "As a result, unlike its human counterpart, ferret TRIM22 may not localise to the nucleus during infection." (PMID 41058038, 2026). "Interestingly, TRIM22 transfection did not inhibit infection of an RNA virus that replicates in the cytoplasm, VSV-GFP." (PMID 33524065, 2021). "Furthermore, cotransfection of TRIM22 with a three-plasmid system for replication-defective HIV-1 resulted in reduced infectious titres of pseudotyped virus, suggesting that TRIM22 inhibited a late stage of HIV-1 pseudoparticle production and/or subsequent infection with the pseudotyped virus." (PMID 22649727, 2012). "Notably, this interaction was significantly enhanced after IAV-H1N1 or IAV-H3N2 infection, without altering the mRNA level of MAVS, suggesting that TRIM22 promoted the antiviral response through interaction with MAVS." (PMID 40162781, 2025).
tumor (33 papers, 2009 to 2026). "TRIM22 can enhance the K63-linked ubiquitination of IKKγ in glioblastoma, effectively activating the NF-κB signaling pathway and triggering tumor cell proliferation and tumor formation." (PMID 40507857, 2025). "In tumor, IL-15 was associated with lymphocyte infiltration in the micro-environment, and we might speculate that TRIM22 mediated this process and further exploration awaits." (PMID 35371994, 2022). "Using animal experiments, we observed that the depletion of TRIM22 delayed tumor growth, but this effect was significantly reversed upon TRIM22 overexpression." (PMID 40075566, 2025). "Histological analyses of tumor tissues using IHC staining revealed that Lyc.HCL effectively reduced the expression of TRIM22 and other key signaling proteins such as JAK2 and p-AKT, further supporting its role in modulating these pathways." (PMID 40075566, 2025). "This provides further evidence that TRIM22 serves as an important mediator of tumor progression in ESCC." (PMID 40075566, 2025). "It is essential to incorporate more detailed clinical data, including tumor stage, metastasis status, and patient age and gender, to assess the potential of TRIM22 as a prognostic biomarker for ESCC." (PMID 40075566, 2025). "The subsequent Western blot analysis of tumor tissues revealed that Lyc.HCL significantly inhibited TRIM22 expression, as well as the expression of JAK2/STAT3 and ERK signaling pathway components." (PMID 40075566, 2025). "In contrast to its tumor-promoting role in GBM and ESCC, a distinct function of TRIM22 as a tumor suppressor has been identified in some cancers." (PMID 40593126, 2025). "TRIM22 is an E3 ligase that can exhibit both tumor-promoting and tumor-suppressive roles in different cancers." (PMID 38199981, 2024). "Our data indicated that TRIM22 functions as a tumor suppressor by directly regulating the level of PHLPP2." (PMID 38199981, 2024). "The xenograft assays suggested that TRIM22 knockdown remarkably enhanced in vivo tumor growth rates as compared to tumors from the control group." (PMID 37415153, 2023). "Lastly, Western blotting assays were conducted to validate TRIM22 protein levels in 8 paired samples of tumor and para-cancerous tissues." (PMID 37415153, 2023). "Consistent with previous reports, the A172 GBM cell line and the primary GBM cell line P1, both of which exhibit TRIM22 overexpression, showed accelerated proliferation 15 days after tumor implantation." (PMID 37258577, 2023). "TRIM22 was shown to confer GBM cell proliferation in vitro and tumor growth in vivo, possibly through TRIM22 E3 ubiquitin ligase activity." (PMID 36139694, 2022). "Some genes (TRIM22/TRIM38/TRIM5/TRIM59) are expressed lower in tumor cells than in other cell types." (PMID 35928444, 2022). "The growth-promoting properties of TRIM22 were also shown to be mediated by IκBα in an orthotopic tumor model." (PMID 32814880, 2021). "Past studies showed that CXCL13, IDO1, PI3, SPP1 and TRIM22 were closely correlated with the prognosis, immunization and chemotherapy sensitivity of tumor." (PMID 34736480, 2021). "Compared with the paracancerous tissues, the expression of CXCL13(P = 0.0093), IDO1(P = 0.0068), PI3(P = 0.0161), SPP1(P = 0.0122) in tumor tissues was significantly increased, while TRIM22(P = 0.0342) was significantly decreased." (PMID 34736480, 2021). "Taken together, these data suggested that the TRIM22 plays an important role in driving tumor growth possibly through its E3 Ub ligase activity." (PMID 32814880, 2021). "In patients with HCC, the average ratio of Trim22 expression in tumor/non-tumor liver tissue was 0.72 (p = 0.008)." (PMID 31979338, 2020). "Additionally, TRIM22 knockdown reduced tumor formation and size, and Lyc.HCL further promoted tumor size reduction in TRIM22-knockdown tumors." (PMID 40075566, 2025).
tumor (continued). "Furthermore, the correlations analysis revealed that five ARGs were associated with tumor purity or seven important immune cells, especially HGF, TRIM22, and SNRPD1." (PMID 37014321, 2023). "Given that tumor heterogeneity may influence drug responses of tumor cells, we thus considered whether TRIM22 expression levels could determine the sensitivity of SKCM cells to Notch1 inhibitors." (PMID 37415153, 2023). "Apart from functioning as a tumor suppressor, TRIM22 could also enhance malignant features in various tumors." (PMID 37415153, 2023). "The function and mechanism of TRIM22 in tumor progression need to be further studied." (PMID 34736480, 2021). "We found that single gene expressions of IDO1, PI3 and TRIM22 could influence the chemotherapy sensitivity of OC patients in "Analysis based on chemotherapy sensitivity of tumor immune-related genes" section." (PMID 34736480, 2021). "The expression of TRIM22 was related to tumor size and depth of invasion in tumor tissues." (PMID 34489426, 2021). "TRIM22 protein expression was related to tumor size and depth of invasion (P < 0.05)." (PMID 34489426, 2021). "Even in the six HCC patients with elevated AFP levels, Trim22 mRNA analysis revealed decreased expression in the tumor compared to the background non-tumor in five of the six patients (83.3%) and most of these patients (4/5) had Trim22 mRNA levels less than 0.5." (PMID 31979338, 2020). "In addition to reduced serum Trim22 expression, Trim22 protein expression was reduced to 72% in liver tumor tissue compared to the background non-tumor tissue in HCC patients." (PMID 31979338, 2020). "TRIM22 staining can be observed in both nuclear and cytoplasmic compartment of tumor cells." (PMID 28977927, 2017). "Therefore, TRIM22 has the potential to inhibit the transcription of several host genes driven by Sp1 and to suppress cellular or even tumor growth." (PMID 26683615, 2015). "Several genes are contained within this interval that might be involved in brain development and/or tumor suppression, including TRIM3 and a cluster of genes encoding the more distantly related TRIM5, TRIM6, TRIM22, and TRIM34 genes." (PMID 19250537, 2009). "TRIM22 (tripartite motif containing 22) is significantly overexpressed in GBM patients, and its knockout reduces tumor growth while enhancing sensitivity to temozolomide (TMZ)." (PMID 40338274, 2025). "Analyses of these databases revealed that TRIM22 expression was downregulated in both total and paired HCC tumor tissues compared to normal tissues, while PHLPP2 expression was upregulated in HCC tumor tissues." (PMID 38199981, 2024). "Several genes associated with the GO category of “Regulation of viral entry into host cells,” TRIM5, TRIM21, TRIM22, and TRIM38 were over-expressed in GBM compared to ODG and non-tumor samples." (PMID 35896929, 2023). "In TCGA database, the expressions of four potential tumor suppressor genes (UBL3, TRIM22, UBE2G2, and MARCH1) were significantly downregulated in tumor samples compared to that in normal lung tissues." (PMID 32296577, 2020). "TRIM22 attenuates BC progression by targeting the JAK-STAT/STAT3 axis through CCS-mediated degradation, resulting in suppressed STAT3 phosphorylation and reduced tumor invasiveness." (PMID 41601694, 2026). "Previous studies also reported that IFI44L, TRIM22, OAS1, OAS2, and MX2 inhibited tumor proliferation and metastasis, indicating that the transcriptional regulation of STAT1/2 could limit the development of OS." (PMID 40956299, 2025). "Furthermore, the IHC scores were negatively correlated between TRIM22 and PHLPP2 in both normal and tumor tissues." (PMID 38199981, 2024). "Last, of all, the subcutaneous xenograft model confirmed that TRIM22 depletion led to enhanced in vivo tumor growth, which could be notably inhibited by KAT2A knockdown, as indicated by tumor volume curves and tumor weight." (PMID 37415153, 2023).
tumor (continued). "In addition, we also downloaded the TRIM22 expression levels from the available microarray data (GSE3189 and GSE15605), and TRIM22 was decreased in tumor samples relative to that in normal samples with P < 0.0001." (PMID 37415153, 2023). "TRIM22 induces SPHK2/MAPK signaling activation in GBM, driving tumor growth and progression." (PMID 37258577, 2023). "Interestingly, TRIM22 stimulates autophagy by promoting BECLIN 1 expression and has also been shown to play a role in driving tumor growth and progression." (PMID 35743294, 2022). "TRIM22 induced NF-κB signaling in GBM, which drives tumor growth and progression." (PMID 32814880, 2021). "Real-time PCR and western blot analysis of the paired tumor/non-tumor liver tissue in HCC revealed a reduced expression of Trim22 in the tumor tissue." (PMID 31979338, 2020). "The relative ratio of tumor/non-tumor mRNA expression of Trim22 was less than 1.0 in 14 of 21 patients (66.6%) and most of them had Trim22 levels less than 0.5 (11 of 14, 78.5%)." (PMID 31979338, 2020). "Interestingly, our data on exosomal protein profiles from treated Caco-2 showed an enrichment of upregulated proteins involved in tumor etiopathogenesis, including CRC (CD59, CRP, CTSD, HMMR, LY6K, TRIM22), and in cell cycle control (BRAF, CDC2, ERBB2)." (PMID 25594007, 2014). "In addition to liver tissue protein expression, the relative expression of Trim22 mRNA in tumor tissue compared to non-tumor tissue was also reduced in most of the HCC cases we examined." (PMID 31979338, 2020). "Using the different sets of tumor and non-tumor tissues from non-HCC patients with liver metastasis not infected with HBV, we showed by western blotting analysis that Trim22 protein expression in tumor tissue was not different from that in the non-tumor tissue background." (PMID 31979338, 2020).